TLR4 (toll like receptor 4)
Diseases named in the same sentence as TLR4 in open-access papers (continued):
Sharing a sentence is not in itself a finding about the gene and the disease.
uveitis (25 papers, 2009 to 2025). An inflammatory process affecting a part of or the entire uvea. "Adoptive transfer of MDSCs in the IRBP-induced uveitis model downregulated the TLR4-mediated innate immune response and decreased pathogenic T-cell activation." (PMID 37878302, 2023). "The preferential expression of TLR4 on tissue macrophages within the iris and ciliary body suggests a novel mechanism for the initiating factors and immunopathogenesis of uveitis, particularly HLA-B27-associated AAU." (PMID 19347047, 2009). "In this study, we investigated whether there were any associations between TLR4 polymorphisms and uveitis with sarcoidosis." (PMID 20011079, 2009). "The aim of this study was to investigate whether TLR4 polymorphisms were associated with sarcoidosis-related uveitis in a Japanese population." (PMID 20011079, 2009). "This study investigated whether TLR4 polymorphisms were associated with susceptibility to sarcoidosis-related uveitis in Japanese patients." (PMID 20011079, 2009). "The expression of Toll-like receptor 4 (TLR4), preferably by cells in the anterior region of the eye, may explain the apparent susceptibility of anterior uvea to disruption of the blood–ocular barrier and development of uveitis." (PMID 34831393, 2021). "In 2013, upregulated expression of TLR2/TLR4 was found in macrophages isolated from BD patients, and that TLR2/TLR4-mediated IL-1β was upregulated in patients with active uveitis when stimulated with peptidoglycan/LPS." (PMID 35359926, 2022). "LPS activated toll-like receptor (TLR-4) expression and induced innate immune response leading to uveitis." (PMID 35909558, 2022). "Our previous studies on the acute animal models found that LPS-Toll-like receptor 4 (TLR4) signal transduction on macrophages plays an important role in the acute episode of uveitis." (PMID 34056011, 2021). "rno-miRNA-30b-5p mimics can reduce the expression of IL-10 and TLR4 genes and proteins, thereby affecting the pathogenesis of uveitis." (PMID 32582189, 2020). "Administration of gold nanoparticles (AuNPs) was found to decrease LPS-induced eye inflammatory response in a rat model of endotoxin-induced uveitis, which is determined by a decrease in TLR4 content and NF-κB activation." (PMID 30711007, 2019). "Our study demonstrates that rno-miR-30b-5p influences the development of uveitis by regulating the level of IL-10 and TLR4 positive cells, thereby playing a role in the pathogenesis of uveitis." (PMID 30510488, 2018). "It would be interesting to investigate how rno-miR-30b-5p regulates IL-10 and TLR4 and thus influence the pathogenesis of uveitis." (PMID 30510488, 2018). "Previous study has demonstrated a higher expression of TLR4 in vivo during endotoxin-induced uveitis (EIU) in macrophages." (PMID 30510488, 2018). "Our results indicate that rno-miR-30b-5p can influence on the pathogenesis of uveitis by regulating the expressions of IL-10 and TLR4." (PMID 30510488, 2018). "All these findings suggest that both TLR4 and IL-10 play a critical role in the pathogenesis of uveitis." (PMID 30510488, 2018). "The uveitis model induced by LPS similarly activates a Toll Like Receptor (TLR4) initiated signaling cascade." (PMID 28066796, 2016). "To investigate the potential role of TLR4 in the pathogenesis of uveitis, we established C3H/HeN (wild type) mouse model, and cultured peritoneal macrophages in vitro." (PMID 22837708, 2012). "The results presented here have demonstrated that the expression of TLR4 in the iris is upregulated during endotoxin-induced uveitis." (PMID 19347047, 2009). "Rno-miR-30b-5p is downregulated in spleen, lymph nodes, and eye tissues in rats with experimental autoimmune uveitis, regulates the levels of IL-10 and TLR4, influences both IL-10 and TLR4 positive cell proportion within cell clusters, and thus suppresses the development of uveitis." (PMID 30510488, 2018).
uveitis (continued). "Therefore, we further explored the relationship between the expression levels of rno-miR-30b-5p and IL-10 and TLR4 and the development of uveitis." (PMID 30510488, 2018). "It is well known that both IL-10 and TLR4 are involved in the development of uveitis." (PMID 30510488, 2018). "Meanwhile, TLR2, TLR4, and other TLRs are closely related to the pathogenesis of uveitis." (PMID 30510488, 2018). "However, in contrast to TLR2 and TLR9, the mRNA levels of TLR4 were significantly higher in IOTB (73.72 ± 53.33) as compared to non-uveitis subjects (2.44 ± 1.27) (p = 0.05)." (PMID 30218032, 2018). "Second, products of tissue inflammation as endogenous ligands for TLR4 may contribute to the perpetuation of uveitis." (PMID 19347047, 2009). "TLR4 polymorphisms do not play an important role in the development of uveitis in Japanese patients with sarcoidosis." (PMID 20011079, 2009). "Therefore, targeting TLR4 could be explored to suppress the production of proinflammatory cytokines in LPS-induced uveitis." (PMID 34361917, 2021). "Therefore, this study attempted to investigate whether CSF-1 and LRR-1 are involved in endotoxin tolerance in uveitis through the TLR4 pathway and their exact mechanisms." (PMID 32671118, 2020). "Therefore, the next step is to investigate whether CSF-1 is involved in endotoxin tolerance in uveitis and its relationship with TLR4 and NF-κB p65." (PMID 32671118, 2020). "Thus, we infer that TLR4 may also stimulate the production of IL-10 in T lymphocytes and thus influencing the developing processes of uveitis." (PMID 30510488, 2018). "TLR4 is expressed in macrophages as the main specific LPS recognition and cellular activation signaling receptor, which may play a relevant role in starting uveitis." (PMID 26078494, 2015). "This may be a mechanism for the perpetuation of uveitis and the progression to chronic inflammation because the products of tissue inflammation further stimulate the immune cells that have infiltrated the eye via TLR4." (PMID 19347047, 2009). "To determine this, we utilised endotoxin-induced uveitis (EIU), a self-resolving model of acute Toll-like receptor 4 (TLR4)-mediated ocular inflammation, that following a single inflammatory insult generates acute immune cell tissue infiltration." (PMID 31993055, 2019). "For instance, metaDEGs of the uveitis only group comprise genes that are involved in the innate immune response, such as chemokine receptors (CX3CR1, CCR1, and CCR2), and Toll-like receptors (TLR4, TLR7, TLR8, and the TLR4 homologous receptor, CD180)." (PMID 40270958, 2025). "Also, TLR4 stimulation showed similar proliferative response between IOTB and non-uveitis (p = 0.72) or non-TB uveitis subjects (p = 1.0) but a higher response than in non-uveitis TB subjects (p = 0.03)." (PMID 30218032, 2018). "However, our results could not completely rule out the possibility that the TLR4 signaling pathway plays a role in the development of uveitis in patients with sarcoidosis." (PMID 20011079, 2009). "Further, mRNA levels of TLR4 were similar between IOTB and non-TB uveitis groups (21.73 ± 8.25) (p = 0.42)." (PMID 30218032, 2018).
HIV-1 infection (24 papers, 2009 to 2025). The type species of lentivirus and the etiologic agent of acquired immunodeficiency syndrome (AIDS). "It has been shown that SNP rs4986790 (1063A/G) and the G allele of SNP rs4986791 in the TLR4 gene are also risk factors for HIV-1 infection and are associated with increased viral load." (PMID 41305532, 2025). "Obviously, further studies are needed to confirm the association of SNPs in the TLR4 gene and vulnerability (susceptibility) to HIV-1 infection in different population groups." (PMID 41305532, 2025). "Then, we performed a meta-analysis by collecting data from eligible studies to evaluate the association between rs4986790 SNP of the TLR4 gene and susceptibility to HIV-1 infection." (PMID 33396586, 2020). "It is known that stimulation of macrophages through TLR3 or TLR4 reduces their susceptibility to HIV-1 infection, but the mechanism is not well understood." (PMID 23028330, 2012). "In addition, a functional variation of TLR4, namely, the rs4986790 single nucleotide polymorphism (SNP) (D299G), contributes to risk of HIV-1 infection in an Indian population." (PMID 33396586, 2020). "To validate whether the rs4986790 SNP of the TLR4 gene is associated with susceptibility to HIV-1 infection, we collected three studies that contain genetic information on ethnic backgrounds and allele frequencies of rs4986790 SNP of the TLR4 gene from HIV-infected patients." (PMID 33396586, 2020). "ATF4 also mediates TLR4-triggered cytokine production, and it has been shown that the level of TLR4 is increased upon HIV-1 infection." (PMID 38534416, 2024). "In the gene-pathway connections, multiple molecules and kinases for NF-κB signaling (e.g., IKBKB, JUN, FOS, MAP2K2, NFKBIA, TLR4) connected the HIV-1 infection and other inflammatory or anti-viral pathways." (PMID 39283947, 2024). "It has been reported that HIV-1 infection results in dysregulation of the TLR4 response to lipopolysaccharide (LPS) ex vivo." (PMID 37298575, 2023). "HIV-1 infection increases expression of inflammatory markers (TLR4, TNF-α, and NF-κB) and upregulates Sur1 and Trpm4 in astrocytes of Tg26 mouse brain tissues." (PMID 33293383, 2020). "Among TLRs, a previous study reported that TLR4 located on the cell surface was upregulated in response to HIV-1 infection in monocyte-derived macrophage (MDM) and peripheral blood mononuclear cell (PBMC)." (PMID 33396586, 2020). "To this end we investigated the effect of HIV-1 Tat protein on the expression of TLR4 and of SOCS1, a protein associated with HIV-1 infection and disease progression." (PMID 26090662, 2015). "Furthermore, we show by SAMHD1 knockdown that the TLR4-activated pathway potently blocks HIV-1 infection in macrophages specifically via SAMHD1." (PMID 32209460, 2020). "In addition, stimulated TLR4 inhibits HIV-1 invasion, and the rs4986790 single nucleotide polymorphism (SNP) (D299G) of the TLR4 gene contributes to the risk of HIV-1 infection in an Indian population." (PMID 33396586, 2020). "The MDMs, though generally susceptible to HIV-1 infection, are known to become relatively recalcitrant to HIV-1 upon stimulation with the Toll-like receptor 4 (TLR4) agonist polyinosine-polycytidylic acid (poly(I:C)) or Toll-like receptor 4 (TLR4) agonist lipopolysaccharide (LPC)." (PMID 29510515, 2018). "Here we tested whether the immunomodulatory activity of isoB and p7 are also TLR4 dependent and determined their kinetic of release in response to HIV-1 infection." (PMID 27310139, 2016). "Such a mechanism might contribute to the dysregulation of the immune response observed early in HIV-1 infection by hijacking TLR4 pathway to establish a proinflammmatory state which is inefficient for HIV-1 clearance and leads to AIDS pathogenesis development." (PMID 26090662, 2015).
HIV-1 infection (continued). "To evaluate whether the rs4986790 SNP of the TLR4 gene is related to vulnerability to HIV-1 infection, we collected genetic information from HIV-1 patients in previous studies and performed an association analysis with a matched control population obtained from the 1000 Genomes Project." (PMID 33396586, 2020). "Therefore, the activation of innate immunity by LPS-mediated TLR4 signaling might attenuate the CD4-independent HIV-1 infection." (PMID 21541353, 2011). "As a control, the TLR4 inhibitor TAK242 prevented G0 arrest and restored HIV-1 infection after LPS treatment." (PMID 32209460, 2020). "Crucially, the TLR4 inhibitor TAK242 completely prevented G0 arrest and SAMHD1 phosphorylation changes, restoring HIV-1 infection." (PMID 32209460, 2020). "TLR4 is not expressed by pDCs, which produce more IFNα per cell than other cell types, but TLR4 drives IFN-I expression in other cell types, and the proportion of IFNα that derives from pDCs during chronic HIV-1 infection remains uncertain." (PMID 23437155, 2013). "Additional studies indicated that both HIV-1 infection of DCs and DC-mediated virus transmission to CD4+ T cells were reduced upon TLR4 triggering due to secretion of type-I interferons." (PMID 19419540, 2009). "While other studies reported that HIV-1 infection hijacks NFκβ to subsequently stimulate its pathogenesis, our work has provided novel insights suggesting an important role of PSP's antiviral response triggered by the TLR4-NFκβ signaling axis." (PMID 30116757, 2018). "Interestingly, HIV-1 infection of monocyte-derived macrophages and peripheral blood mononuclear cells has been observed to up-regulate TLR-2 and TLR-4 expression." (PMID 28949981, 2017). "The stimulation of TLR3, 7/8 and 9 controls more efficiently HIV-1 infection in the uterus than in other compartments, while TLR4 stimulation does not have a major impact." (PMID 28953320, 2017). "Candidates for factors that induce IFN-I in HIV-1 infection include viral single-stranded RNA, which is recognized by TLR7/8, and bacterial molecules such as LPS, which is elevated in HIV-1 infection and is recognized by TLR4." (PMID 23437155, 2013). "TLR4 sensitivity could be partially due to immune activation of mother-newborn pairs, considering that HAART is known to reduce immune activation, which has been ascribed to intestinal microbial translocation during HIV-1 infection." (PMID 23826189, 2013). "We identified a subset of four miRNAs that were significantly up-regulated in cells stimulated through TLR3 and TLR4 but not through TLR7 and could potentially play a role in modulating susceptibility to HIV-1 infection in this system." (PMID 23028330, 2012). "Our data suggest that engagement of the TLR4-TRIF-type I IFN axis in macrophages can repress virus replication and we wished to determine whether signaling through this axis could contribute to the establishment of persistent low-level or latent HIV-1 infection in macrophages." (PMID 33472928, 2021). "Thus, we assessed inflammasome activation by HIV-1 infection or VbP treatment with and without pretreating THP-1 cells with agonists of TLR1/2 (Pam3CSK4), TLR7/8 (CL075), TLR8 (TL8-506), or TLR4 (LPS)." (PMID 37417868, 2023).
cardiomyopathy (23 papers, 2011 to 2025). A disease of the heart muscle or myocardium proper. "TLR-4 is considered to be the main member of the TLRs implicated in DOX-induced cardiomyopathy that initiates left ventricles (LV) damage." (PMID 32079097, 2020). "TLR-4 deficiency improves left ventricular function and attenuates pathophysiological key mechanisms in cardiomyopathy." (PMID 24971143, 2014). "Similarly, inhibition of TLR4 also mitigates metabolic-associated cardiomyopathy." (PMID 39769189, 2024). "Although no studies have specifically investigated the relationship between FGFR2 and TLR4, research has demonstrated that high glucose -induced activation of FGFR1 is mediated by TLR4 and c-Src in the context of cardiomyopathy." (PMID 40791737, 2025). "A previous study showed that TLR4 knockout alleviates Dox induced cardiomyopathy by inhibition of the inflammatory response, which is completely contradictory with this present study." (PMID 22808256, 2012). "The objective of this study was to evaluate the therapeutic effect of TLR2 and TLR4 blockade on already established Dox induced cardiomyopathy." (PMID 22808256, 2012). "Therefore, TLR4 signaling is thought to be involved in the mechanism contributing to Dox-induced cardiotoxicity, and inhibition of TLR4 is considered to be one the potential interventions against Dox-induced cardiomyopathy." (PMID 37298770, 2023). "Activation of TLR4 occurs in cardiotoxicity, cardiomyopathy, HF, and other cardiac alterations." (PMID 34573046, 2021). "TLR4 is activated in several cardiac alterations, such as cardiotoxicity, cardiomyopathy, and HF." (PMID 34573046, 2021). "Next, we examined whether inflammation mediated the disparate responses of TLR2 or TLR4 inhibition in Dox-induced cardiomyopathy." (PMID 22808256, 2012). "Furthermore, increased TLR4 expression was observed in isolated cardiomyocytes from humans and animals with cardiomyopathies." (PMID 21999911, 2011). "Also, empagliflozin may improve cardiac dysfunction in cardiomyopathy by reducing TLR4 expression in the myocardium." (PMID 36749400, 2023). "The recombinant form of the anti-fibrotic hormone, relaxin (RLX), suppresses the pro-fibrotic influence of TGF-β1 and toll-like receptor (TLR)-4 on NLRP3 inflammasome priming and activity in human cardiac myofibroblasts and mice with cardiomyopathy." (PMID 32848798, 2020). "We identified genes with alternative splicing profiles that were common to cardiomyopathy (PDLIM3, CD36, CLDND1, TTN, FAM126a, TLR4, and CD59)." (PMID 28098235, 2017). "Furthermore, tirzepatide has demonstrated cardioprotective effects against sepsis-induced cardiomyopathy, evidenced by reduced APD and QTc, through targeting the TLR4/NF-kB/NLRP3 pathway." (PMID 39769189, 2024). "This upregulated level of TLR4, though not reaching statistical significance at early time points in mice or when comparing patient cohorts, has been discussed to contribute to toxic side effects in chemotherapy like cardiomyopathy." (PMID 34222016, 2021).
alcohol (22 papers, 2010 to 2025). "Nonetheless, a recent study designed to address the role of neuroimmune signaling in alcohol drinking concluded that TLR4 has minimal impact on the amount of consumed alcohol, but it mediates the acute sedative effects, which might indicate the susceptibility to develop alcohol dependence." (PMID 29690521, 2018). "Naltrexone and naloxone, TLR4 antagonists, are already used clinically to counter the effects of opioids and treat alcohol dependence and are, therefore, known to be safe medications." (PMID 35426035, 2023). "Systemic injection of the TLR4-specific ligand LPS increases voluntary alcohol consumption in mice, and human alcoholics have elevated levels of plasma LPS and TLR4 activation markers." (PMID 30718548, 2019). "Recently, the involvement of TLR4 in alcoholism has been reported." (PMID 24244457, 2013). "In animal models of alcoholism, the administration of the CB2r agonist AM1241 promoted liver regeneration in a thioacetamide (TAA)-induced liver injury model by suppressing TLR4/miR-155/NF-κB p65 pathway." (PMID 35682586, 2022). "To examine the role of the VTA α2/TLR4 signal in binge alcohol drinking, we used the operant DIDMSA protocol developed by the Integrative Neuroscience Initiative on Alcoholism (INIA-West)." (PMID 29690521, 2018). "The data suggest that TLR4 signaling in VTA dopaminergic neurons controls impulsivity related to the regulation of TH expression, likely contributing to the initiation of alcohol drinking and its transition to alcohol dependence." (PMID 27187237, 2016).